NDRG1 (N-myc downstream regulated 1)
Diseases named in the same sentence as NDRG1 in open-access papers (continued):
Sharing a sentence is not in itself a finding about the gene and the disease.
neuroblastoma (continued). "Considering this finding and the data obtained in the present and previous studies, we suggest that the upregulation of NDRG1, which is detected after combined treatment with thiosemicarbazones and GEF or LAP, presents a promising strategy for neuroblastoma treatment." (PMID 36160437, 2022). "We found that in neuroblastoma cells the MYCN/LSD1 complex binds and represses NDRG1 expression." (PMID 27894074, 2017). "In addition to marked NDRG1 activation in the cells treated with thiosemicarbazones alone, these effects were also detected when thiosemicarbazones were combined with GEF or LAP in both neuroblastoma cell lines." (PMID 36160437, 2022). "Importantly, NDRG1 was found to be a positive prognostic factor in neuroblastoma, regardless of the MYCN amplification status, which suggests a functional role of NDRG1 on its own in addition to its role as a marker of N-MYC dysregulation in neuroblastoma." (PMID 35008802, 2021). "In SK-N-SH cells (one of the human neuroblastoma cell lines) expressing NDRG1-S330A (constitutively nonphosphorylated NDRG1; NP-NDRG1), weak and diffusely distributed staining can be observed for each of the adhesion molecules throughout the cytoplasm, including the cell membrane." (PMID 25705664, 2015). "Interestingly, high levels of LSD1 and NDRG1 expression are mutually exclusive in neuroblastoma tumors and NDRG1 expression levels are significantly lower in MYCN-amplified NB samples." (PMID 27894074, 2017).
ovarian carcinoma (16 papers, 2011 to 2025). A malignant neoplasm originating from the surface ovarian epithelium. "Genes involved in the cellular response to hypoxia, including NDRG1, are associated with a significantly poorer prognosis in breast and ovarian cancers." (PMID 22067903, 2011). "The risk model composed of GSK3α/β, HSP70, MEK1, MTOR, BAD, and NDRG1 could predict survival prognosis of ovarian cancer patients efficiently and help disease management." (PMID 35840928, 2022). "Biological experiments have revealed that NDRG1 was associated with ovarian cancer metastases." (PMID 26735889, 2016). "The CD105 molecule is involved in ovarian cancer metastasis through the activation of EMT via the inhibition of NDRG1, E-cadherin." (PMID 38791431, 2024). "The PGRMC1 (Membrane-associated progesterone receptor component 1) is known to be involved in ovarian cancer as well as PTGIS (Prostacyclin synthase) and the Protein NDRG1 known to modulate genes involved in ovarian cancer metastasis." (PMID 37775701, 2023). "In vitro work in ovarian cancer has shown NDRG1 knockdown increases cell proliferation and inhibits apoptosis suggesting a tumour suppressor role in ovarian cancer." (PMID 36213122, 2022). "Our risk model, composed of six proteins (GSK3α/β, HSP70, MEK1, MTOR, BAD, and NDRG1), can predict survival of ovarian cancer patients effectively, thereby helping prognosis monitoring and decision making." (PMID 35840928, 2022). "ILF3 is another important gene in the NDRG1 module, where it has been shown to be involved in ovarian cancer." (PMID 26735889, 2016). "In colorectal, prostate, cervical, and ovarian cancers, NDRG1 plays important roles in preventing tumor progression and metastasis, which suggests that NDRG1 has a role as a tumor suppressor, metastasis suppressor, or both in these cancers." (PMID 26431493, 2015). "Bioinformatic analysis revealed that NDRG1, CYBRD1, and MT2A expressions upregulated and were associated with poor prognosis of ovarian cancer patients in the platinum-based treatment group, whereas upregulation of ERBB4 and ANK3 correlated with improved prognosis." (PMID 38987777, 2024). "It is reported that NDRG1 gene may play an important role in the invasion and metastasis of cervical and ovarian cancer through its downstream CLCA2 gene." (PMID 36280802, 2022). "In ovarian cancer, increased NDRG1 could enhance drug sensitivity through induction of hypoxic stress response." (PMID 35840928, 2022). "The risk model composed of six proteins (GSK3α/β, HSP70, MEK1, MTOR, BAD, and NDRG1) could predict the survival prognosis of ovarian cancer efficiently and had a prominent predictive performance." (PMID 35840928, 2022). "This suggests that NDRG1 may still have undiscovered roles in ovarian cancer." (PMID 38987777, 2024). "CN variations in WISP1 have been associated with endometrial adenocarcinoma whereas NDRG1 has been reported as a tumor suppressor in ovarian carcinogenesis across distinct ovarian subtypes, therefore it is thus not surprising to find these genes as top hits across ovarian cancer subtypes." (PMID 32316560, 2020). "We used NDRG1, a downstream tumor suppressor gene of the MYC signaling pathway in ovarian cancer, as an example." (PMID 27029057, 2016). "Notably, cell experiments were performed to validate the roles of NDRG1, CYBRD1, and MT2A in cisplatin resistance in ovarian cancer." (PMID 38987777, 2024). "In addition, in vitro experiments showed that NDRG1, CYBRD1, and MT2A played a role in ovarian cancer cisplatin resistance." (PMID 38987777, 2024). "Importantly, p85β-overexpressing ovarian cancer cells demonstrated coordinated enhanced phosphorylation of PDK1, SGK3, and NDRG1." (PMID 32385243, 2020).
ovarian carcinoma (continued). "Our results may imply that NDRG1 promotes EMT in ovarian cancer, not just in cell lines." (PMID 27029057, 2016).
melanoma (14 papers, 2004 to 2025). A malignant, usually aggressive tumor composed of atypical, neoplastic melanocytes. "The highest NDRG1 staining was detected in intradermal nevi (benign mole), which suggests the anti-metastatic roles of NDRG1 in melanoma." (PMID 40378957, 2025). "In conclusion, we reported the association of HRGs with patient prognosis in melanoma and screened for novel gene signatures, including FBP1, NDRG1, GPI, IER3, B4GALNT2, BGN, PKP1, and EDN2." (PMID 37422626, 2023). "The importance of NDRG-1 in melanoma is not well known; strong NDRG-1 staining was seen in melanoma samples compared to in nevus." (PMID 31594284, 2019). "We also demonstrated the HIF-1β and NDRG-1 expressions to be significantly different in nevus than in melanoma in paraffin-embedded tissue study." (PMID 31594284, 2019). "Our studies showed that NDRG-1 mRNA expression was initially upregulated, and then was downregulated in experimental hypoxic conditions in melanoma cells." (PMID 31594284, 2019). "Skin cancer melanoma cells showed the most intensive staining with Ndrg1 antibody, and a benign skin lesion nevus had very limited Ndrg1 staining." (PMID 15341671, 2004). "However, NDRG1 mRNA levels were downregulated in a metastatic melanoma cell line (WM-266-4) compared to primary melanoma cell lines (WM-115) under normoxic conditions." (PMID 40378957, 2025). "For example, expression of NDRG1 (N-mycdownregulated gene 1) is higher in BrM-initiating breast tumour cells, and expressionof PLEKHA5 (Pleckstrin homology domain-containing A5) in melanoma is associatedwith brain-specific metastasis." (PMID 35225863, 2022). "Although NDRG-1 was downregulated in melanoma compared to in nevus, we could not detect any difference between H-scores of primary and metastatic melanomas in tissue samples." (PMID 31594284, 2019). "Compared to fibroblasts, prognostic genes were significantly up-regulated in 3 human melanoma cell lines, especially GPX2, DERL3, NDRG1, and DTL (p < 0.05)." (PMID 41409301, 2025). "Of interest, the upregulation of total PKCα protein and downregulation of total β-catenin by the NDRG1-inducing therapeutics, DpC and DFO, was also demonstrated in SK-Mel-28 melanoma cells." (PMID 38815861, 2024). "For the level of mRNA expression in the TCGA database and melanoma cell lines, SLC39A14, PSMB4, CRELD2, CDKN2A and TIMP1 were higher in SKCM tissues than in normal skin tissues, and NDRG1, ATF3, and JUND had an opposite trend." (PMID 36226170, 2022). "The result demonstrated that CCLB (P = 0.018), INHA (P < 0.001), and NDRG1 (P = 0.001) were significantly upregulated in metastatic melanoma, while LHB (P = 0.001) was significantly downregulated when compared with primary melanoma." (PMID 33688507, 2021). "Examining melanoma, immunohistochemical staining studies have revealed that NDRG1 was expressed in the cytoplasm, but not in the nucleus, and its expression was upregulated in the primary melanoma cell line (WM-115) after 1, 4, and 8 h of hypoxia." (PMID 40378957, 2025).
breast tumor (13 papers, 2013 to 2025). "These correlations indicate that NDRG1 expression is strongly associated with breast tumors with high glycolytic and angiogenic gene expression." (PMID 29898756, 2018). "Additional investigation indicated that NDRG1 on chromosome 8q24 was markedly amplified in metastatic and basal-like breast tumors." (PMID 40378957, 2025). "We further retrospectively analyzed NDRG1 protein expression levels in a total of n = 211 breast tumor samples (n = 71 TNBCs and n = 140 Luminal BCs) and normal regions non adjacent to the tumor (n = 10, distance > 2 cm) by IHC." (PMID 39736699, 2024). "The TBX2-KAP1-HP1 complex co-represses NDRG1 (N-Myc downstream regulated 1), which is a breast tumor suppressor." (PMID 35159030, 2022). "Accordingly, the variance in NDRG1 expression between the methylated and unmethylated tissues was statistically significant in the breast tumors and corresponding normal tissues (p = 0.000)." (PMID 23899187, 2013). "In this sense, it is interesting that NDRG1 was found to promote lung colonization of breast tumor cells in cooperation with KIAA1199 as part of the effects of Coco on tumor cell dormancy 61 and to be upregulated in a subpopulation of slow-cycling breast tumor-initiating cells within CTCs." (PMID 36594086, 2023). "Therefore, the MSP results of the breast tumor cell lines were proven with both the data of NDRG1 expression and sequencing data." (PMID 23899187, 2013). "Other up-regulated proteins of interest with possible roles in regulating breast tumor cell progression included DPYSL2, FAM129B, IL18, NDRG1, NME1, and SERPINB5." (PMID 28174229, 2017). "Our results showed that NDRG1 mRNA expression was not amplified in 45 out of 87 breast tumors, while only 10 normal tissues lost NDRG1 expression in the corresponding normal samples." (PMID 23899187, 2013).
glioblastoma (12 papers, 2015 to 2024). The most malignant astrocytic tumor (WHO grade IV). "In this context, NDRG1 provides cancer cell resistance to apoptosis by stabilizing DNA repair proteins that counter the apoptotic-inducing activity of alkylating drugs in glioblastoma." (PMID 37298315, 2023). "In this sense, it has been recently reported in glioblastoma that GSK3β expression leads to NDRG1 degradation as a tumor suppressor and, conversely, NDRG1 overexpression induced GSK3β degradation as a bidirectional regulatory mechanism." (PMID 36594086, 2023). "In glioblastoma, alkylating anticancer drugs are less effective in cancer cells that express high levels of NDRG1." (PMID 37298315, 2023). "In glioblastoma, mTORC2 regulates the phosphorylation of NDRG1 (on Thr346)." (PMID 37298315, 2023). "Radiotherapy and alkylating drugs induce NDRG1 mRNA and protein in glioblastoma." (PMID 37298315, 2023). "Furthermore, NDRG1 overexpression inhibited glioblastoma cell growth by decreasing expression of cyclin D1/E and CDK 2/4 in a cell‐cycle signalling pathway." (PMID 34965023, 2021). "Collectively, these data suggest that NDRG1 might have properties of a tumor suppressor gene in glioblastoma, but that upregulation by genotoxic treatment will impair the response to chemotherapy and lead to reduced overall survival." (PMID 31485792, 2019). "Recent studies suggested that NDRG1 positively regulates and stabilizes DNA repair enzymes MGMT, APEX1, and PKNP, thereby driving temozolomide (TMZ) resistance in human glioblastoma and acute lymphoblastic leukemia (AML)." (PMID 38970106, 2024). "However, overall survival of glioblastoma patients was not significantly affected by NDRG1 expression levels." (PMID 31485792, 2019).
triple-negative breast carcinoma (12 papers, 2013 to 2025). An invasive breast carcinoma which is negative for expression of estrogen receptor (ER), progesterone receptor (PR), and human epidermal growth factor receptor 2 (HER2). "In a research conducted by López-Tejada and colleagues, both total NDRG1 and p-NDRG1 (Thr346) positivity and subcellular localisation were crucial for the survival of patients with triple-negative breast cancer." (PMID 40332138, 2025). "Of interest, nitric oxide (NO) has also been demonstrated to upregulate NDRG1 expression in triple-negative breast cancer cells (HCC 1806) and inhibit cellular migration." (PMID 40378957, 2025). "NDRG1 expression was also observed to be higher in triple-negative breast cancer versus non-triple-negative counterparts." (PMID 40378957, 2025). "Analysis of multiple independent data sets has shown that NDRG1 levels are statistically significantly higher in tumors with aggressive molecular subtypes, such as triple-negative breast cancers." (PMID 37847564, 2023). "Taken together, these findings provide insights into the transcriptional regulation axis of HJURP/YAP1/NDRG1 in triple-negative breast cancer progression and therapeutic response." (PMID 35459269, 2022). "We have also elaborated on SK4 mechanism of action in ovarian and triple negative breast cancer cells in which we see differential modes of cell death and involvment of tumour suppressor NDRG1." (PMID 36213122, 2022). "In future, it would be of interest to study NDRG1 in the context of other subtypes beyond triple-negative breast cancers." (PMID 32612361, 2020). "This is the first study to show that mitochondria in triple-negative breast cancer mediate significant up-regulation of a number of genes, and silencing of NDRG1 leads to significant reduction in proliferation." (PMID 32612361, 2020). "NDRG1 was observed to be amplified and up-regulated in a large proportion of the basal subtype of triple-negative breast cancer among invasive breast carcinoma patients." (PMID 32612361, 2020). "Among 9 genes which were significantly down-regulated, NDRG1 was most affected and was also confirmed to be amplified and up-regulated in a significant proportion of triple-negative breast cancer patients." (PMID 32612361, 2020). "Knockdown of NDRG1 expression significantly decreased proliferation of SUM-159 triple-negative breast cancer cells." (PMID 32612361, 2020). "Furthermore, in vitro examination of the overexpression of NDRG1 in triple-negative breast cancer cell-line, MDA-MB-463 demonstrated suppressed invasiveness." (PMID 40378957, 2025). "Thus, overexpression of full-length NDRG1 promotes tumor growth in highly aggressive triple-negative breast cancer." (PMID 38983911, 2024). "And HJURP/YAP1/NDRG1 axis could affect cell proliferation and chemotherapy sensitivity in triple-negative breast cancer." (PMID 35459269, 2022). "In triple-negative Breast Cancer (TNBC), XBP1 promotes cancer development, and in these models, it acts together with HIF as a positive regulator of NDRG1 expression." (PMID 40332138, 2025). "However, NDRG1 overexpression led to reduced proliferation in estrogen receptor-positive (ER+) MCF7 cells, while having the opposite effect in triple-negative breast cancer (TNBC) cells, indicating a cell type-dependent response." (PMID 38983911, 2024). "In triple-negative breast cancer (TNBC), the pleiotropic NDRG1 (N-Myc downstream regulated gene 1) promotes progression and worse survival, yet contradictory results were documented, and the mechanisms remain unknown." (PMID 36594086, 2023). "Therefore, our research mainly focuses on exploring the progression of triple-negative breast cancer and determines the important role of the HJURP/YAP1/NDRG1 transcriptional regulation axis in triple-negative breast cancer." (PMID 35459269, 2022).